STK11 (serine/threonine kinase 11)
Diseases named in the same sentence as STK11 in open-access papers (continued):
Sharing a sentence is not in itself a finding about the gene and the disease.
cancer (continued). "STK11 is a cancer suppressor gene that has been demonstrated to be associated with poor prognosis." (PMID 38731247, 2024). "While individuals without mutations in STK11 exhibit a reduced risk of developing cancer and typically experience a later onset of symptoms, those with the uncommon splicing mutation c.921-1G > C in intron 7 of STK11 face significant health challenges due to its detrimental effects." (PMID 39767561, 2024). "STK11 germline mutations and increase in the risk for cancer." (PMID 38800180, 2024). "Cancers harboring serine threonine kinase (STK11) alteration or SWI/SNF-related, matrix-associated, actin-dependent regulator of chromatin, subfamily B, member 1 (SMARCB1) mutation are conventionally considered as treatment-refractory to immune checkpoint inhibitors or chemotherapy, respectively." (PMID 36776287, 2023). "It is possible, however, that the reduced survival may also be secondary to the significant cancer-related weight loss associated with STK11/LKB1 mutation status." (PMID 37092555, 2023). "Interestingly, in the NCI 60 assay, CVM-1125 exhibited high cytotoxicity in the two NSCLC cancer cell lines (A549 and H460) carrying STK11 loss-of-function mutation." (PMID 37351538, 2023). "We next mapped all the STK11/LKB1 variants associated with cancer-induced weight loss." (PMID 37092555, 2023). "This suggests CVM-1118 may have the potential to treat cancer patients carrying STK11- or NF2-deficient mutation–via targeting TRAP1 and inhibiting the activation of mTOR/AKT signaling pathways." (PMID 37351538, 2023). "The types and locations of cancer-related STK11 gene variants were evaluated." (PMID 36033506, 2022). "One study found 36 malignant tumors in 119 patients with germline STK11 mutations." (PMID 35163129, 2022). "Similarly, approximately 30% of breast cancer sporadic cancers were associated with low STK11 levels." (PMID 36661676, 2022). "Moreover, PD-L1 expression was also suppressed in cancer cells, indicating that STK11-deficient KRAS mutations lead to anti-PD-1/PD-L1 resistance in cancer cells." (PMID 35070984, 2021). "STK11/LKB1 deficiency promotes cancer cell growth, motility, and invasion." (PMID 34831355, 2021). "Loss of function of the tumor suppressor STK11 (LKB1) has been observed in many types of cancer." (PMID 32647375, 2020). "STK11 is a multifunctional gene associated with several types of cancer, including HNC." (PMID 32911741, 2020). "Somatic loss of function STK11 mutations has been found in several cancer types." (PMID 32911741, 2020). "Moreover, we also assessed the correlation between STK11 mutation and immune cell infiltration by using the Genomics of Drug Sensitivity in Cancer (GDSC) database to identify a candidate drug to treat LUAD with STK11 mutations." (PMID 33425731, 2020). "Here, we assessed the relevance of STK11 mutations regarding immune cell infiltration, drug sensitivity, and cellular processes, which can provide insights for the development of individualized cancer treatments." (PMID 33425731, 2020). "GSEA enrichment analysis showed that the STK11 mutations were associated with multiple cancer-related pathways, including oxidative phosphorylation, unfolded protein response, peroxisome, protein secretion, Wnt/beta catenin signaling and PI3K/AKT/mTOR signaling." (PMID 33425731, 2020). "The gene encoding LKB1 (called STK11 in humans) had been previously identified as being involved in Peutz–Jeghers syndrome, a rare inherited cancer susceptibility; humans with this syndrome are almost always heterozygous for loss-of-function mutations in STK11." (PMID 31288625, 2019). "Loss of STK11 has been shown to correlate with increased cancer development." (PMID 28109268, 2017). "Subsequently, somatic STK11 mutations have been reported in sporadic cancers including NSCLC." (PMID 26625312, 2017).
cancer (continued). "The different germline variants of the STK11 gene predispose patients to different disease manifestations (e.g., numbers of polyps and times of onset of mucocutaneous pigmentation) and different risks of cancer." (PMID 26607058, 2015). "Similarly, limited knowledge of the pathogenicity of missense variants in STK11 may cause a subset of NSCLC patients to miss potentially helpful therapies that are in development for STK11-mutated cancers." (PMID 40791513, 2025). "Thus, we hypothesised that cancers harbouring dual KRAS mutation/STK11 inactivation might be particularly vulnerable to targetting mTOR signalling." (PMID 40069402, 2025). "When STK11 is mutated it may lead to Peutz-Jeghers Syndrome and many types of cancer." (PMID 33070285, 2020). "Regarding KRAS, STK11 mutation is significantly enriched in KRAS G12C-mutated tumors compared to KRAS non-G12C-mutated tumors (20.59% vs. 5.95%, [OR] = 4.10) across all cancer types, indicating their potential relationship." (PMID 41541668, 2026). "The primary pathogenic mechanism involves loss-of-function mutations in the STK11/LKB1 gene, which disrupts multiple signaling pathways, including AMPK-mTOR, Wnt/β-catenin, and PI3K/AKT, leading to polyp formation and increased cancer susceptibility." (PMID 41573642, 2025). "Particularly, ACSL4 exhibited the most predominant negative correlation with PEBP1/STK11 co-expression across multiple cancer types, suggesting an inhibitory role in fatty acid metabolism." (PMID 40806276, 2025). "On the other hand, OV demonstrated an entirely opposite trend, with strong positive correlations between PEBP1/STK11 co-expression and the majority of glucose metabolism genes, pointing to a unique metabolic signature in this cancer type." (PMID 40806276, 2025). "Among these, PEBP1/STK11 co-expression strongly negatively correlates in all cancer types with enzymes that increase the biosynthesis of fatty acids such as members of the ACSL family (ACSL1, ACSL3, ACSL4, ACSL5, and ACSL6)." (PMID 40806276, 2025). "Collectively, we associated the redox status mediated by loss-function mutations of KEAP1 or STK11 to immune evasion and immunotherapeutic resistance by suppressing STING/MDA5 expression and interferon signaling of cancer cells." (PMID 41378285, 2025). "The results showed a statistically significant negative correlation between the ESTIMATE score and PEBP1 and STK11 co-expression patterns across the majority of cancer types." (PMID 40806276, 2025). "Resolving VUS to pathogenic or benign will both enable a non-invasive means of diagnosing PJS via a blood test and also support a genotype-driven approach to therapy for cancers involving somatic STK11 variation." (PMID 40791513, 2025). "A study analyzing tissue from 4446 cancer patients found that 1.35% had STK11 alterations either in the tissue, ctDNA, or both." (PMID 40647497, 2025). "For example, individuals can be monitored and regularly screened for cancer-related phenotypes associated with CHEK2 and STK11 (individual 1) and SDHA (individual 4)." (PMID 40195116, 2025). "For example, the potential to restore immunotherapeutic sensitivity to STK11-driven cancers by inhibiting CoREST deacetylase activity has been explored via Tango Therapeutics’ compound TNG26060, or via inhibitors of AXL, CDK4/6, or STAT361–63." (PMID 40791513, 2025). "Most of the immune stimulators analyzed demonstrated a complex, cancer type-dependent expression pattern, suggesting that their correlation with PEBP1/STK11 is influenced by the specific TME of each cancer." (PMID 40806276, 2025). "Somatic alterations in STK11 are most prevalent in lung cancer, however, they are also observed in other cancer types such as breast, head, and neck cancers." (PMID 39011112, 2024).
cancer (continued). "STK11 is the primary pathogenic gene associated with PJS, and many studies have determined a link between its variants and increased cancer risk." (PMID 39080663, 2024). "A total of 75 index cases with CPs and a personal/family history of cancer were analyzed to identify genetic alterations in major hereditary polyposis-associated genes (APC, BMPR1A, MUTYH, PTEN, SMAD4, STK11)." (PMID 39518056, 2024). "Tango Therapeutics generated a STK11-deleted MC38 mouse cancer model and, through an in vivo CRISPR screening platform, found that HDAC1 is a key target mediating immune evasion in STK11-deficient tumors." (PMID 39655075, 2024). "Loss-of-function mutations in STK11 disrupt the normal functioning of the gene, causing PJS-related traits, including gastrointestinal polyps as well as a higher risk of cancer to emerge." (PMID 38800180, 2024). "Research focused on NSCLC with KRAS driver mutations, in particular, the KRAS p.G12C mutation, shows that co-mutations in STK11 and/or KEAP1 make these cancers notably resistant to standard therapies, including targeted and immune-based treatments." (PMID 39001451, 2024). "For patients with KRAS WT cancer across all treatment types in the 2L setting, significantly shorter OS was observed in patients with mSTK11-mKEAP1 vs STK11 WT-KEAP1 WT (3.5 vs 8.3 months; aHR, 1.83; 95% CI, 1.35–2.49; p < 0.001)." (PMID 37069542, 2023). "In a recent study of cancer-associated VTE, somatic mutations of KRAS and STK11 were associated with thromboembolic events." (PMID 37370734, 2023). "All identified STK11 mutations were null mutations that were associated with more severe PJS phenotypes and cancers." (PMID 36874343, 2023). "Mutations in STK11, CDKN2B, KEAP1, CTNNB1, MET, and KRAS were associated with a significantly increased risk of cancer-associated thrombosis." (PMID 38069251, 2023). "We next attempted to generalize the importance of STK11/LKB1 to CC development with the use of a different primary cancer using syngeneic, immunocompetent in vivo models." (PMID 37092555, 2023). "A similar pattern of results was observed in patients with KRAS G12C–positive cancer: median OS was significantly shorter in patients with mSTK11-mKEAP1 vs STK11 WT-KEAP1 WT (6.4 vs 15.0 months; aHR, 1.93; 95% CI, 1.35–2.75; p < 0.001)." (PMID 37069542, 2023). "Genomic profiles of cancer patients identified that tumor-induced mutations in KRAS, STK11, KEAP1, CDKN2B, CTNNB1, and MET are significantly associated with cancer-associated thrombosis." (PMID 37046748, 2023). "Loss of LKB1 or STK11 and stimulation of KRAS work in concert to enhance serine metabolism and further cancer progression." (PMID 36831413, 2023). "First, the subinteractomes of these ORF proteins contain proteins associated with ‘cancer hallmark’ and oncoproteins (e.g., the case of C5orf24 and its protein partners XPO1, PBX1, MYC, CIC, GOPC, CREB1 and STK11)." (PMID 37373333, 2023). "NSCLC with STK11 and/or KEAP1 mutations represents one of most aggressive types of cancer, characterized by resistance to standard cytotoxic chemotherapy or radiotherapy." (PMID 37675220, 2023).
cancer (continued). "Our results build on these previous findings and further underscore the poor prognosis and high unmet medical need that exists in patients with aNSCLC with co-occurring mutations in STK11 and KEAP1, with either KRAS WT cancer or KRAS G12C–positive cancer." (PMID 37069542, 2023). "Defective STK11/AMPK activity contributes to phenotypic manifestations of PJS, including polyp formation and cancer susceptibility metabolism." (PMID 36874343, 2023). "Most importantly, the loss-of-function mutations of STK11 and NF2 are potential biomarkers of CVM-1118 which can be applied in the selection of cancer patients for CVM-1118 treatment." (PMID 37351538, 2023). "For patients with KRAS WT cancer across all treatment types in the 1L setting, significantly shorter median OS was observed in patients with mSTK11-mKEAP1 vs STK11 WT-KEAP1 WT (5.8 vs 10.1 months; aHR, 1.81; 95% CI, 1.44–2.26; p < 0.001)." (PMID 37069542, 2023). "The data show that even in these highly CVM-1125-sensitive cancer cell lines, silencing of STK11 or NF2 was able to induce further reduction in cell viability compared with scramble control." (PMID 37351538, 2023). "However, our analyses of the relationships between genotypes and phenotypes involved the observation that the same STK11 genetic variant could be associated with a variable cancer status in different PJS families, or in different members of the same family, or even within a single patient." (PMID 36033506, 2022). "Stk11 mutation (and the consequent LKB1 loss) directly induces epigenetic changes and confers a proliferative advantage to cancer cells." (PMID 35406531, 2022). "This narrative review provides an overview of the STK11/LKB1 gene and its role in cancer development." (PMID 35165542, 2022). "Additional panels, including the Myriad Genetics myRisk panel and the Color Hereditary cancer panel, expand beyond germline DDR mutations while incorporating other potential genes of interest, including PTEN, SMAD4, and STK11." (PMID 33947030, 2021). "In conclusion, while STK11/LKB1 favored cell survival under stress conditions, it has been shown that STK11/LKB1 loss enhanced cancer cell proliferation under energy deprivation." (PMID 34831355, 2021). "Inactivating somatic mutations of STK11 have been observed in different types of solid tumors, especially in NSCLC, where it modulates cancer cell differentiation, invasion, and metastasis." (PMID 34831355, 2021). "In this review, we first describe the biological function of STK11/LKB1 and the role of its inactivation in cancer cells." (PMID 34831355, 2021). "The AMPK activator, LKB1, is encoded by the gene STK11, which is mutated or deleted in many cancers." (PMID 32850483, 2020). "Five cancer genes mutated at greater frequency in AA LUAD tumors (MAX, ACTN2, PRKD1, PTPRC, STK11) remained significant after accounting for mutation burden and age at diagnosis." (PMID 32952607, 2020). "We found that these CLCLs exist even in pivotal cancer-related genes, such as the STK11, NF1, SMARCA4, and PTEN genes." (PMID 32887687, 2020). "Remarkably, despite the role that STK11 plays in regulating various hallmarks of cancer there is little information on the inhibition afforded by microRNAs." (PMID 32911741, 2020). "Known cancer genes such as COL1A1 or STK11 were affected by duplications and other known genes such as CDKN2A, JAK2, PRDM1, FBXW7, or GOLGA5 were affected by deletions in several tumors of this subcluster." (PMID 32604718, 2020). "CLCLs were found to occur even in key cancer genes, such as the STK11, NF1, SMARCA4, and PTEN genes." (PMID 32887687, 2020).
cancer (continued). "Various cancer types have been shown to carry druggable targets for mTOR inhibitors, including mutations in MTOR, TSC1, TSC2, NF1, PI3KCA, PIK3CG, STK11, and RHEB." (PMID 31443247, 2019). "Therapeutic strategies aimed at targeting the downstream targets of the mTOR signaling pathway common to S6K1 and S6 are considered as potential therapeutic targets against STK11-related cancer." (PMID 30975222, 2019). "Several cancer-related genes such as STK11, SMARCA4, and RUNX1 were located within the HMA-resistance-specific CNAs." (PMID 28052028, 2017). "In addition, although heterogeneous mutational status of STK11 may be masked in large-scale genomics datasets, using Cancer Cell Line Encyclopedia datasets we observed increased palbociclib sensitivity for cell lines with low STK11 copy number and mRNA expression." (PMID 28205554, 2017). "Among these, five novel mutations in cancer-related genes (KDR, STK11, MLH1, KRAS, and PTPN11) were detected in ES, and these mutations were confirmed with traditional Sanger sequencing." (PMID 27077911, 2016). "PJS is another inherited polyposis syndrome, caused by a germline mutation in the STK11 gene (also known as LKB1), with an increased cancer risk, both intraintestinal and extraintestinal, and it is typically accompanied by mucocutaneous skin pigmentations." (PMID 27108415, 2016). "On one hand, individuals with missense mutations in STK11 typically have a later onset for PJS symptoms, but have cancer risks similar to the ones with truncating mutation." (PMID 27821076, 2016). "We further added to the complement of known RAS-activating mutations in observing mutations in BRAF (two MC), as well as previously unreported potentially RAS-activating alterations in FGFR2, ERBB2, and STK11, each affecting a single carcinoma." (PMID 25986173, 2015). "p70S6K is frequently amplified and overexpressed in cancer cells, and its hyperactivation has been associated with the frequently mutated tumor suppressor LKB1 (STK11)." (PMID 24069582, 2013). "CDK5R2, NEK9, PRKCA, PXK and STK11 have significant effects on growth of cancer cells in all cancer cell lines." (PMID 22761558, 2012). "Confining the analysis to LKB1/STK11 mutation carriers, the probability of developing cancer by age 65 is 47% (95% CI: 27–73%), SMR of all and gastrointestinal cancers of 13.2 (95% CI: 0.5–27.1, P<0.001) and 32.0 (95% CI: 0.5–81.8, P<0.001), respectively." (PMID 12865922, 2003). "To further our knowledge about the relation between genotype and cancer risk in PJS, we have related disease expression to LKB1/STK11 status in 33 families." (PMID 12865922, 2003). "Downregulation of STK11 promotes tumorigenesis across various cancers." (PMID 41051525, 2025). "Suppression of STK11 has been shown to promote cancer cell migration, invasion, and metastasis." (PMID 41051525, 2025). "Our study suggested that KEAP1 and STK11 shared common mechanism in immune regulation, which is associated with enhancement of redox phenotype and the subsequent inhibition of STING/MDA5 expression and the downstream interferon signaling in cancer cells." (PMID 41378285, 2025). "The reduction in STK11/LKB1 expression in normal cells leads to the development of cancer." (PMID 40018404, 2025). "This is even more true because some of the predisposing variants may carry a risk for other cancers or diseases later in life, examples being mutations in BRCA2, STK11, BLM, and CDKN2A, among other genes." (PMID 40340749, 2025).